NTRK1 (neurotrophic receptor tyrosine kinase 1)
Diseases named in the same sentence as NTRK1 in open-access papers (continued):
Sharing a sentence is not in itself a finding about the gene and the disease.
cancer (continued). "This could be corroborated by our proteomics functional analysis, where we found, for instance, a higher abundance of HADH, PLOD3 and ACAT1 (lysine degradation) and PFKL, NTRK1, PDHB and PDHA1 (central carbon metabolism in cancer) in control piglets compared to UL." (PMID 38409238, 2024). "Notably, TIE1, KIT, NTRK1, FGFR3, CSF1R, and INSRR were shared by both cancers." (PMID 34944663, 2021). "A direct comparison with the cancer genome atlas (TCGA) adult series cannot be made, but it is worth noting that NTRK3 rearranged PTCs, as well as ALK and NTRK1, were not consistently and homogeneously defined as BRAF-like or RAS-like tumors." (PMID 34206589, 2021). "There are no records of comparison between NTRK1 and NTRK3 fusion-positive carcinomas in the literature." (PMID 33923728, 2021). "NGS testing with Foundation Medicine Inc assays does not cover the whole exome/genome, so while NTRK1/2/3 are interrogated, including all exons and specific introns, the description of the genomic characteristics of NTRK fusion-positive cancers cannot be considered exhaustive." (PMID 34285332, 2021).
neurodegenerative disease (15 papers, 2012 to 2025). A disorder of the central nervous system characterized by gradual and progressive loss of neural tissue and neurologic function. "The age-dependent regulation of NTRK1/NTRKA and p75/NGFR in mammalian brain results in a reduced response of the cholinergic neurons to neurotrophic factors and is thought to play a role in the pathogenesis of neurodegenerative diseases." (PMID 32575701, 2020). "In mammalian brain, the age-dependent downregulation of NTRK1/NTRKA and p75/NGFR results in a reduced response of the cholinergic neurons to neurotrophic factors and is thought to play a role in the pathogenesis of neurodegenerative diseases." (PMID 32575701, 2020).
adenocarcinoma (6 papers, 2009 to 2024). A common cancer characterized by the presence of malignant glandular cells. "The two cases included one case with mixed ACC and adenocarcinoma, who was found to have NTRK1 fusion (case 17#), and another case with pure ACC on histology (#18)." (PMID 39410042, 2024). "One case had mixed ACC and adenocarcinoma (NTRK1 fusion positive, #17) and the other case had pure ACC on histology (#18)." (PMID 39410042, 2024). "NTRK1 is a TRKA kinase; thus, TRKA kinase inhibitors have the potential to be used in the treatments of NTRK1-rearranged adenocarcinomas." (PMID 28894699, 2017).
CNS tumors (4 papers, 2021 to 2025). "Except for a paediatric spinal HGG (GBM-like) and a DIG, which harboured NTRK1 fusions, all other CNS tumours in this study exhibited NTRK2 fusion, consistent with its status as the most common NTRK family member exhibiting fusion in CNS tumours." (PMID 39014476, 2024). "Comparison of the normalized read counts from RNA-Seq data revealed elevated NTRK1 expression, over 7 standard deviations from the mean, relative to NTRK1 expression for CNS tumors within the NCH cohort (N = 138)." (PMID 34863095, 2021). "Apart from targeting the neuronal BDNF pathway, entrectinib gains importance in therapy and diagnostics of CNS tumors: The 2021 WHO classification identifies a new class of infant-type hemispheric glioma presenting with receptor tyrosine kinase fusions with ALK, ROS1, NTRK1/2/3, or MET." (PMID 36357661, 2022).
genetic disorder (4 papers, 2021 to 2025). "CIPA is a rare genetic disorder caused by mutations in the NTRK1 gene." (PMID 39687654, 2024).
hematological malignancies (4 papers, 2017 to 2021).
benign tumors (3 papers, 2014 to 2024). "NTRK1 and NTRK3 fusions were indeed more common in the Dutch population (n = 4 and n = 5, respectively), mostly in benign tumors, and all of these patients were tested for the differential diagnosis." (PMID 35328221, 2022).
autosomal recessively inherited disorder (1 paper, 2015). "CIPA is an autosomal recessively inherited disorder, resulting from the presence of 2 NTRK1 pathogenic variants." (PMID 25984678, 2015).
kidney disease (1 paper, 2020). "Thus, it is possible that NTRK1 mutation in this family might also contribute to the kidney disease in this family." (PMID 33235206, 2020).
NTRK1 also shares sentences with these, for which no sentence is quoted: ovarian carcinoma (23 papers); infection (15); diabetes (12); medulloblastoma (11); osteoarthritis (10); psoriasis (10); cognitive decline (9); cystitis (9); hepatocellular carcinoma (9); pheochromocytoma (9); Pruritus (8); Anxiety (7); triple-negative breast carcinoma (7); astrocytoma (6); cervical cancer (6); myocardial infarction (6); Obesity (6); oral cancer (6); pulmonary fibrosis (6); retinal degeneration (6); asthma (5); Cerebral ischemia (5); endometriosis (5); leiomyosarcoma (5); lymph node metastasis (5); medullary thyroid cancer (5); prostatitis (5); anaplastic large cell lymphoma (4); Anosmia (4); cholangiocarcinoma (4).
A further 293 diseases each share a sentence with NTRK1 in 4 papers or fewer.